IL2 (interleukin 2)
Diseases named in the same sentence as IL2 in open-access papers (continued):
Sharing a sentence is not in itself a finding about the gene and the disease.
thymoma (7 papers, 2006 to 2024). A neoplasm arising from the epithelial cells of the thymus. "To quantify HCMV-specific IgG activation of FcγRI and FcγRII, we used mouse BW thymoma cell lines expressing chimeric human FcγRs that secrete mouse IL-2 upon IgG engagement as a quantitative readout for FcγR activation." (PMID 35763348, 2022). "In this system, mouse thymoma BW cells expressing chimeric CEACAM1 composed of the extracellular portion of human CEACAM1 fused to the mouse CD3ζ chain secrete mouse IL-2 upon binding and activation of CEACAM1 by specific ligands." (PMID 34336716, 2021). "In EL-4 mouse thymoma cells, IL-2 secretion levels as measured by the growth rate of CTLL-2 cells reduced from 15.38% to 0.89% with the highest growth rate drop of 14% observed with 20 μg Perna." (PMID 16412227, 2006). "The transfection of EL4 thymoma cells, which constitutively express IL-2 mRNA, using DNA with p21 in the sense and antisense direction resulted in modulation of T cell proliferation." (PMID 17096842, 2006). "In addition, compared with the proportion of CD8+ cells in thymocytes of patients with MG without thymoma, those inpatients with MG with thymoma increased significantly during the incubation period with IL-2." (PMID 38378668, 2024).
airway hyperresponsiveness (6 papers, 2009 to 2019). "The nasal administration of IL-2 and IL-18 induced airway hyperresponsiveness, pulmonary eosinophilia and goblet cell hyperplasia in wild type mice, but not in Rag2-deficient mice." (PMID 30717382, 2019). "The combination of IL-2 and IL-18 was recently found to prevent airway hyperresponsiveness and airway inflammation in a mouse model, likely through IL-12-mediated induction of IFN-γ production in NK cells." (PMID 23283012, 2009). "In this study, we show that short-term intratracheal use of IL-2 combined with glucocorticoid alleviates antigen-induced airway inflammation and reduces airway hyperresponsiveness by expanding antigen-nonspecific Treg cells, with a decrease in T helper 2 (Th2) cells and Th2-associated cytokines." (PMID 27527926, 2016). "In contrast, transfer of IL-2-differentiated CD8+ T cells cultured in the presence of 1,25D3 (100 nM or 1 μM) fails to restore airway hyperresponsiveness (AHR) or airway inflammation." (PMID 26750596, 2016).
amyotrophic lateral sclerosis (6 papers, 2021 to 2026). Amyotrophic lateral sclerosis (ALS) is a neurodegenerative disease characterized by progressive muscular paralysis reflecting degeneration of motor neurons in the primary motor cortex, corticospinal tracts, brainstem and spinal cord. "Some neuroprotective effects of low-dose IL-2 treatment have been found in AD mice and in amyotrophic lateral sclerosis (ALS) patients." (PMID 38407500, 2022). "More recently, a randomized, placebo-controlled phase IIa trial was conducted in patients with amyotrophic lateral sclerosis (ALS) to evaluate the therapeutic effect of three 5-day cycles of low-dose IL-2 therapy." (PMID 33868284, 2021). "A randomized placebo-controlled pilot phase-II clinical trial called Immuno-Modulation in Amyotrophic Lateral Sclerosis was carried out to test safety and activity of low-dose interleukin-2 in 36 amyotrophic lateral sclerosis patients (NCT02059759)." (PMID 34409288, 2021). "A randomized, placebo-controlled pilot phase-II clinical trial, Immuno-Modulation in Amyotrophic Lateral Sclerosis (IMODALS) was carried out to understand the safety and activity of ld-IL-2 in ALS patients." (PMID 34409288, 2021). "Interestingly, in patients with amyotrophic lateral sclerosis (ALS), dysregulation of Tregs was also shown, which was reversed after ex vivo expansion with rapamycin/IL-2 and intravenous adoptive transfer of Tregs with concomitant subcutaneous IL-2 injection." (PMID 41596238, 2026). "Moreover, significant induction of G-CSF, IL-2, IL-15, IL-17, MCP-1, MIP-1α, TNF-α, and VEGF levels has been observed in amyotrophic lateral sclerosis (ALS) patients." (PMID 36052093, 2022).
ankylosing spondylitis (6 papers, 2020 to 2025). An autoimmune chronic inflammatory disorder characterized by inflammation in the vertebral joints of the spine and sacroiliac joints. "Moreover, studies indicate Treg functional impairments in ankylosing spondylitis, potentially due to IL-2 deficiencies, reduced STAT5 phosphorylation, decreased FOXP3 expression, and increased CpG methylation in the CNS2 region of the FOXP3 gene." (PMID 39131703, 2024).
bipolar disorder (6 papers, 2015 to 2025). A disorder of the brain that causes unusual shifts in mood, energy, activity levels and the ability to carry out day-to-day tasks. "In patients with bipolar disorder, a significant inverse relationship between SANS scores and IL-2 (rs = −.660, p = 0.020) was identified." (PMID 29803226, 2018). "For instance, recent studies have indicated that low-dose interleukin-2 (IL-2) therapy may exert antidepressant effects, particularly in treatment-resistant cases of MDD and bipolar disorder." (PMID 40002916, 2025). "Levels of IL-2, IL-4, IL-10 and IFN-γ were not significantly different from controls in either mania or euthymia, but current study numbers mean no conclusions can be reached regarding levels in bipolar depression; further studies are required." (PMID 30113291, 2018).
candidiasis (6 papers, 2022 to 2025). Infection with the organism Candida. "IL-1 inhibitors (anakinra, canakinumab, and rilonacept), IL-2 inhibitors (daclizumab, and basiliximab), and IL-4 inhibitors (dupilumab) have rarely been associated with Candida infection." (PMID 38605952, 2024). "T-cell depletion, for example, is most commonly linked to candidiasis in HIV patients and is decreased by inhibiting interleukin-2, blocking the Th1 differentiation, and promoting its apoptosis." (PMID 36000133, 2022). "In a murine model of invasive candidiasis, genes also clustered towards biological pathways reflective of generalized immune and defense response, as well as upregulation of inflammatory cytokines, including IL2, later in the disease course." (PMID 39666613, 2024). "Additionally, cytokines such as Interleukin-2 (IL-2), IL-6, IL-10, and Interleukin-17A (IL-17A) were significantly elevated in patients with bloodstream Candida infections compared to bacterial BSIs, demonstrating their capacity to differentiate between fungal and bacterial pathogens." (PMID 40137168, 2025). "Furthermore, IL-12 regulates T cell proliferation and differentiation, with IL-2 enhancing interferon-gamma (INF-γ) production through the januskinase signal transducer and transcription factor (JAK-STAT) pathway during Candida infection." (PMID 38605952, 2024).
cardiomyopathy (6 papers, 2016 to 2025). A disease of the heart muscle or myocardium proper. "Chagasic patients with cardiomyopathy show decreased production of IL-2 by peripheral blood leucocytes." (PMID 27242702, 2016). "This is rather unique because the patient developed a near-lethal ventricular arrhythmia, 11 days after IL-2 therapy was discontinued, and additionally required a temporary pacemaker with possibility of a permanent defibrillator given the severity of her cardiomyopathy." (PMID 29399586, 2018). "However, serum IL-2 levels have been reported to increase in chagasic patients with cardiomyopathy." (PMID 27242702, 2016). "This indicates that the relationship between MCP-1, VEGF, and IL-2 is related to cardiomyopathy, not FD." (PMID 40072051, 2025).
chronic obstructive pulmonary disease (6 papers, 2016 to 2025). A chronic and progressive lung disorder characterized by the loss of elasticity of the bronchial tree and the air sacs, destruction of the air sacs wall, thickening of the bronchial wall, and mucous accumulation in the bronchial tree. "Furthermore, another study on patients with chronic obstructive pulmonary disease by Rubing Mo and collaborators found that LPS induces lncRNA GAS5 expression and release of IL-2, IL-6, IL-10, and TNF-α." (PMID 37047453, 2023).
cryptococcal infection (6 papers, 2015 to 2025). "Supporting this, enhancing Tregs via IL-2/anti-IL-2 antibody complexes or disrupting Treg-mediated suppression of Th2 cells accelerates disease progression and mortality in invasive cryptococcosis models." (PMID 40806563, 2025). "During cryptococcal infection, stimulated lung-infiltrating T lymphocytes secrete both Th1 (IFNγ, IL-2) and Th2 (IL-4, IL-5, IL-10) cytokines." (PMID 29333430, 2017). "The main protective cytokines produced during cryptococcal infections include IFNγ, IL-12 and IL-2." (PMID 29333430, 2017). "Studies that sought to explore the pharmacotherapeutics of IFN-gamma also helped shed light on the possible therapeutic benefit of systemic treatment with interleukin 2 (IL-2) and anti-CD20 agents in preventing cerebral cryptococcal infection." (PMID 38571832, 2024). "Since Th2 cells generated during pulmonary cryptococcal infection expressed high levels of the alpha chain of the high affinity IL-2 receptor (CD25), we sought to use IL-2 complexes to boost the Th2 cell response." (PMID 25764512, 2015).
cutaneous leishmaniasis (6 papers, 2013 to 2019). Leishmaniasis affecting the skin. "Protective immunity against VL, as in case of cutaneous leishmaniasis is dependent on IL-12 driven type 1 response characterized by IL-2 and IFN-γ production, which induces parasite death." (PMID 31189939, 2019). "A prior study indicated that PLA2 appears to be a factor in the progression of cutaneous leishmaniasis, since macrophages treated with PLA2 presented elevated levels of prostaglandin E2 (PGE2) (an inflammatory lipid mediator) and inhibited levels of IL-2, a cytokine associated with Th-1 response." (PMID 26609302, 2015). "Recent studies have also shown that individuals with severe cutaneous leishmaniasis have reduced CD8+ T cell numbers with the ability to produce IFN-γ and IL-2." (PMID 24349591, 2013). "Previous studies revealed that protection against L. major infection in mice and healing of cutaneous leishmaniasis in humans correlates with the priming of multifunctional Th1 CD4+ T cells that simultaneously secrete high amounts of IFN-γ, IL-2, and TNF-α." (PMID 23840706, 2013).
diabetic nephropathy (6 papers, 2016 to 2024). "Serum bilirubin levels are positively correlated with the levels of the antioxidative enzymes as superoxide dismutase, catalase, and glutathione peroxidase, while it is inversely correlated with C-reactive protein, TNF-α, interleukin (IL)-2, IL-6, and IL-10 release in diabetic kidney disease." (PMID 35327498, 2022). "Long-term treatment with amygdalin reduced inflammation by downregulating the expression of cytokines, including IL-2 and IFN-γ, in the renal tissues of rats with diabetic nephropathy." (PMID 37559205, 2023). "The inhibitory effects on the levels of interleukin-2, interleukin-6, interleukin-10, and tumor necrosis factor-α in serum and kidney revealed the protection of PHC against diabetic nephropathy." (PMID 27034961, 2016).
diffuse large B-cell lymphoma (6 papers, 2016 to 2023). "Serum IL-6 and IL-2 were associated with adverse clinical features and worse outcomes in diffuse large B-cell lymphoma." (PMID 36016687, 2022). "IL-2 polymorphism conferred an almost threefold increased risk of diffuse large B-cell lymphoma (OR: 2.64, 95% CI: 1.35-5.15) and a fourfold increased risk of indolent subtypes (OR: 4.34, 95% CI: 1.20-15.7)." (PMID 28713071, 2018). "Interestingly, high expression of IL-2 correlated with better survival also in the cohort of diffuse large B cell lymphoma patients." (PMID 27477778, 2016). "Doxorubicin-induced senescence promoted the recruitment of Treg cells and myeloid-derived suppressor cells to mediate apoptotic resistance in diffuse large B-cell lymphoma (DLBCL) via pro-inflammatory cytokines, such as IL-2, IL-6, IL-8, IL-10, IL-35, TGFβ, and VEGF." (PMID 36834846, 2023).
eczema (6 papers, 2017 to 2025). "When unadjusted levels of growth factors and detectability of cytokines were assessed, we found that detectable IL13 and IL2 in breast milk were significantly less often associated with eczema at 6 months." (PMID 28538696, 2017). "Lastly, PHF11, a transcriptional activator of the Th1 effectors interleukin-2 (IL2) and interferon-γ (IFNG), is predicted to be associated to eczema." (PMID 28598986, 2017). "Clinical studies suggest that the mechanism of MTMZM in treating eczema may be related to regulating the expression of IL-2, IL-4, IL-10, and γ-IFN; therefore, it can improve the body's immunity and reduce inflammatory response." (PMID 40933470, 2025).
Encephalopathy (6 papers, 2017 to 2025). Encephalopathy is a term that means brain disease, damage, or malfunction. "However, the IL-2 levels in the plasma and CSF remained unchanged in patients with prolonged FSs with or without encephalopathy during the acute stage." (PMID 29017522, 2017).
endotoxemia (6 papers, 2017 to 2025). "TNF‐α is the main cytokine synthesized during endotoxemia and is considered to be responsible for the expression of IL‐1β, IL‐2 and IL‐6." (PMID 28684640, 2017). "LPS is a marker of endotoxemia, which promotes skeletal-muscle-insulin resistance by proinflammatory cytokine expression of TNF-α, interleukin-1 (IL-1), interleukin-2 (IL-2), and IL-6." (PMID 32751533, 2020). "↑ Veillonellaceae, endotoxemia, and inflammation (IL-6, TNF-α, IL-2, and IL-13) in cirrhotic patients with HE vs. without HE.↑ Enterobacteriaceae, Alcaligeneceae, and Fusobacteriaceae and ↓ Ruminococcaceae and Lachnospiraceae compared with controls." (PMID 37367929, 2023).
fibrosis (6 papers, 2019 to 2025). the formation of excess fibrous connective tissue in an organ or tissue in a reparative or reactive process. "In relation to cytokine levels in F0 group, statistically significant decrease in group of patients with fibrosis (F1, F3) was recorded for IFNγ (p = 0.039), IL-2 (p = 0.033), IL-17 (p = 0.039) and IL-13 (p = 0.047)." (PMID 31318916, 2019). "IL-2 participates in RPE cell migration, extracellular matrix (ECM) synthesis, TGF-β2 expression, indicating that IL-2 makes a constructive effect on the fibrosis of macular degeneration." (PMID 33061811, 2020).
helminth infection (6 papers, 2013 to 2023). "The resistant phenotype of the IL-6-deficient mouse could be fully reversed by administration of an anti-IL-2:IL-2 complex, rescuing the Treg-cell phenotype, inhibiting Ag-specific Th2 responses, and restoring susceptibility to chronic helminth infection." (PMID 24185641, 2014). "IL-2, IL-7 and IL-15 could possibly serve as lymphoid growth factors and could underlie novel strategies for immune recovery and the optimization of immune therapies in helminth infections." (PMID 29795573, 2018). "It is expected that a heavy burden of helminth infection results in diminished IL-2 and interferon-γ (IFN-γ) responses." (PMID 37568838, 2023). "The role of CD4+ and CD8+ T cell subset distribution and the association between memory T cell subsets and the common γc cytokines (IL-2, IL-4, IL-7, IL-9 and IL-15) in helminth infections has not been explored well." (PMID 29795573, 2018). "However, the effects of helminth infection on common γc cytokine—IL-2, IL-4, IL-7, IL-9 and IL-15- levels have not been explored in Ss infection." (PMID 29795573, 2018).
Hemophagocytosis (6 papers, 2014 to 2025). Phagocytosis by macrophages of erythrocytes, leukocytes, platelets, and their precursors in bone marrow and other tissues. "Bone marrow biopsy revealing hemophagocytosis, elevated ferritin and triglycerides, high interleukin-2, fever and cytopenia, confirmed the diagnosis of HLH." (PMID 40508215, 2025). "The diagnosis was confirmed by the laboratory findings of elevated CD163 and IL-2, as well as hemophagocytosis identified in a bone marrow biopsy." (PMID 34795304, 2021).
leptospirosis (6 papers, 2019 to 2024). A contagious bacterial infection caused by spirochetes of the genus Leptospira. "A previous systematic review showed elevated levels of cytokines (IL-1β, IL-2, IL-4, IL-6, IL-8, IL-10, TNFα) in severe human leptospirosis compared with mild leptospirosis." (PMID 39729468, 2024). "Especially, TNF-α and the interleukins IL-1β, IL-2, IL-4, IL-6, IL-8, and IL-10 were elevated in severe leptospirosis cases, whereas TNF-α, IL-6, IL-8, IL-10, interferon-γ, and soluble TNF receptor 1 were elevated in high fatality cases." (PMID 35237527, 2021). "Several earlier studies have identified significant expression of IL-1β, IL-2, IL-4, IL-6, IL-8, IL-10 and TNF-α in severe leptospirosis." (PMID 35584087, 2022). "Significantly higher concentrations of IL-1β, IL-2, IL-4, IL-6, IL-8, IL-10, IL-17A, and TNF-α were found in sera of leptospirosis patients." (PMID 35927283, 2022). "IL-1b, IL-2, IL-4, IL-6, IL-8, IL-10 and TNF-α levels were found to be significantly higher in severe than in mild leptospirosis." (PMID 32264832, 2020).
listeriosis (6 papers, 2013 to 2022). A bacterial infection caused by Listeria monocytogenes. "Therefore, these compounds could be considered for use as a potential treatment for listeriosis by inhibiting proteins such as, IL2, MAPK1, SRC, EGFR, PTPRC, TNF, IL1B, and ERBB2." (PMID 36671206, 2022). "Short-term exposure of naïve mice with IL-2 complexes containing the anti-IL-2 mAb clone S4B6 has also been shown to enhance resistance and immunity against subsequent Listeria monocytogenes infection." (PMID 27391012, 2016).
lymph node metastasis (6 papers, 2007 to 2026). "In the IL-2 subgroup, one patient received additional concomitant systemic therapy during intralesional treatment following the development of a regional lymph node metastasis." (PMID 40171522, 2025). "The results indicated a significant correlation between IL-2 (P ═ 0.025), IL-4 (P ═ 0.005), IL-8 (P ═ 0.009), IL-10 (P ═ 0.017), IL-12p70 (P ═ 0.002), IL-17 (P < 0.001), TNF-α (P < 0.001), and IFN-γ (P ═ 0.026) and lymph node metastasis." (PMID 38920620, 2024). "The results showed that there is a statistically significant correlation between the expression level of IL-2 (P ═ 0.010), IL-4 (P ═ 0.028), IL-10 (P ═ 0.011), IL-12p70 (P ═ 0.034), IL-17 (P ═ 0.024), TNF-α (P ═ 0.003), and IFN-γ (P ═ 0.007) and lymph node metastasis." (PMID 38920620, 2024). "The expression levels of IL-2 (P ═ 0.010), IL-4 (P ═ 0.028), IL-10 (P ═ 0.011), IL-12p70 (P ═ 0.034), IL-17 (P ═ 0.024), tumor necrosis factor (TNF)-α (P ═ 0.003), and interferon (IFN)-γ (P ═ 0.007) were related to lymph node metastasis." (PMID 38920620, 2024).
measles (6 papers, 2014 to 2023). A highly contagious viral infection caused by the measles virus. "Interestingly, the concentration of IL-2 had a positive effect on the level of IgG for measles and mumps viruses." (PMID 36851738, 2023). "A Th1 cytokine profile, with elevations in peripheral blood gamma interferon (IFN-γ) and interleukin-2 (IL-2), is present during the measles prodrome, whereas measles convalescence is characterized by elevations in Th2 cytokines, such as interleukin-4 (IL-4) and interleukin-5 (IL-5)." (PMID 32085446, 2020). "For example, HLA class I and HLA class II genotypes and SNPs in cytokine/cytokine receptor genes (IL12B, IL12RB1, IL2, IL10) and the cell surface measles virus receptor the CD46 gene, have been reported to affect measles vaccine-induced immunity." (PMID 34683414, 2021).